MTOR (mechanistic target of rapamycin kinase)
Diseases named in the same sentence as MTOR in open-access papers (continued):
Sharing a sentence is not in itself a finding about the gene and the disease.
tumor (continued). "We pathologically analyzed p38 and mTOR activation via a similar appraisal strategy in a case-to-case manner, and found synchronized changes in Zscan4 expression and p38/mTOR activation in the tumour stroma of NSCLC patients." (PMID 29712904, 2018). "p-AKT and p-mTOR cytoplasmic expression in primary PSCC correlated with both a higher tumour grade and a more aggressive tumour subtype, while their nuclear expression associated with negative lymph node status and a lower tumour grade, respectively." (PMID 29902261, 2018). "The acute activation of mTOR by eccentric contraction is maintained in cachectic muscle but can be disassociated from protein synthesis in tumour bearing mice." (PMID 29417752, 2018). "Here we investigated the role of SNX10 in regulating amino-acid metabolism and mTOR signaling pathway activation, as well as the impact on the tumor progression of mouse CRC." (PMID 29867114, 2018). "Preclinical studies including panel of HER2+ BC cell lines and mouse models accentuated the benefit of dual targeting of mTOR and Src, where in combination, the recurrence of tumor growth following the treatment cessation is further delayed." (PMID 29765318, 2018). "The dual PI3K/mTOR inhibitor NVP-BEZ235 showed anti-angiogenic activity in tumor mouse models of breast and renal cell cancers and glioma." (PMID 29104248, 2017). "We found that FiBYL719 administration leads to prolonged and tumour-specific inhibition of the PI3K/AKT/mTOR pathway, which resulted in durable control of tumour growth." (PMID 28194032, 2017). "Our results provide with a molecular explanation for the modest results obtained when mTOR inhibitors are used as anti-tumour therapy, as rapamycin treatment promotes survival during nutrient-restricted conditions." (PMID 28112156, 2017). "Activated AMPK phosphorylates the tuberous sclerosis complex (an inhibitor of mammalian target of rapamycin (mTOR)), leading to the up regulation of its activity and subsequent mTOR inhibition and tumor suppression." (PMID 28423712, 2017). "In our study, the tumor micromorphology appeared to undergo hyalinization with cell nuclei devitalization after treatment with the PI3K/mTOR inhibitor; this is similar to that seem with radiation, trabectedin, and doxorubicin therapy, as reported by others." (PMID 28903344, 2017). "Many types of human tumors up-regulated expression of the mTOR complex 1 which regulated cell growth and metabolism according to their cellular energy levels, and suppression of the mTOR pathways inhibited tumor cell growth via 4E–BP1 and p70S6K molecules." (PMID 28464864, 2017). "This study revealed that activation of the mTOR signaling pathway contributed to RA-XII-induced tumor cells death." (PMID 29137114, 2017). "In order to determine the molecular mechanisms underlying PTRF mediated tumor suppression, the AKT/mTOR signaling pathway was tested by western blotting in our established cells lines." (PMID 27203393, 2017). "Reduced vessel density in these models was associated with decreased level of HIF-1 (hypoxia-inducible factor 1) and VEGF, confirming the role of mTOR in hypoxic tumor response." (PMID 29104248, 2017). "Blockage of mTOR activity by an mTOR inhibitor, everolimus, exhibits an effect of anti-tumor development and is approved by the FDA for the treatment of several types of cancers." (PMID 28811537, 2017). "Immunohistochemical analysis also showed that LNT substantially inhibited PI3K and mTOR expression in LNT-treated tumor tissues compared with the control." (PMID 29156828, 2017).
tumor (continued). "These in vivo studies further verified that administration of cryptolepine inhibits tumor growth by modulating AMPKα1/2/mTOR, and reducing the c-Myc/SIRT1/PGC-1α signaling cascade involved in mitochondrial dynamics and biogenesis." (PMID 28473727, 2017). "Since 2012, five case reports have been published in the relevant English literature that present successful cases of using everolimus, an inhibitor of the mammalian target of rapamycin (mTOR), to trigger tumor regression in neonatal patients with CR." (PMID 28780710, 2017). "The importance of mTOR for tumour cell growth is now widely accepted and several agents are available or under investigation that selectively target mTOR." (PMID 28417948, 2017). "PTEN exerts its tumor suppressor function by acting as a negative regulator of the mTOR/Akt signaling pathway." (PMID 29221206, 2017). "In conclusion, we have provided evidence that CD164 promotes the growth of lung tumor-initiating cells with stem cell properties and induces tumor growth and drug resistance through Akt/mTOR signaling." (PMID 28903328, 2017). "Next, we tested the role of the dual PI3K/mTOR inhibitor in tumor growth and radiosensitivity of an OML1-R xenografted mouse model." (PMID 28978144, 2017). "In a pharmacodynamic evaluation of temsirolimus in patients with newly diagnosed advanced HNSCC, Akt/mTOR pathway biomarkers were evaluated in tumor and peripheral blood mononuclear cells (PBMCs)." (PMID 28108737, 2017). "These tumor suppressor functions of mTORC1 highlight the complexity of the action mechanisms of central cell growth regulators, such as mTOR, and how microenvironmental cues influence their function." (PMID 28616576, 2017). "The high mTOR activity related biological advances in tumour proliferation were inhibited by rapamycin both in vitro and in vivo in the studied heterozygous IDH1 mutant cells." (PMID 28578659, 2017). "Dual inhibition of PI3K and mTOR can block the loop and enhance therapeutic effectiveness, and inhibition has been shown to improve tumor radiosensitivity by impairing DNA damage repair and normalizing tumor vasculature." (PMID 28280736, 2017). "Activity of the small molecule inhibitors against AKT and mTOR kinases used in this study have also been tested in a number of other tumour types." (PMID 28915623, 2017). "The effects of R7 on PI3K/PTEN/Akt/mTOR signaling were examined in HeLa cells, and R7 anti-tumor activity was confirmed in a mouse xenograft model." (PMID 29312623, 2017). "More recently, it has been found that the activity of the mechanistic target of rapamycin (mTOR) signaling cascade plays a critical role for the induction of senescence in many tumor cell models." (PMID 28678198, 2017). "These genetic aberrations in the mTOR pathway and its interconnected pathways are present across many different tumor types (COSMIC database)." (PMID 28903445, 2017). "mTOR is a serine/threonine kinase downstream of PI3K-AKT that acts through the mTOR complexes 1 and 2 (mTORC1 and -2) to induce transcription of many genes involved in altered tumor cell metabolism." (PMID 28724379, 2017). "The PTEN (phosphate and tensin homolog) phosphatase is a negative regulator of mTOR activity and acts as a tumor suppressor." (PMID 28640831, 2017). "SAHA-induced mTOR inactivation as a major regulator of autophagy activating the remaining autophagic core machinery is by far the most reported pathway in several tumor models." (PMID 30563957, 2017). "Conditional cell depletion studies have partially confirmed the role of mTOR in endothelial cells and tumor angiogenesis." (PMID 29104248, 2017). "In our patient, disease progression on multiple lines of cytotoxic chemotherapy suggests that targeted inhibition of mTOR pathway was critical in inducing tumor response." (PMID 28302097, 2017). "Combined inhibition of EGFR and mTOR exhibited synergistic cytotoxicity in several human tumor cell lines." (PMID 29234489, 2017).
tumor (continued). "TSC is caused by decreased or absent expression of the genes TSC1 (hamartin) or TSC2 (tuberin) resulting in an aberrant mTOR-signaling and subsequent tumor growth." (PMID 29232371, 2017). "Temsirolimus is a specific inhibitor of mTOR, which interferes with the synthesis of proteins that regulate the proliferation, growth, and survival of tumor cells." (PMID 29179457, 2017). "ATO activated p38 MAPK and subsequently inhibited the Akt/mTOR signaling pathways to suppress tumor cell growth." (PMID 28241849, 2017). "In contrast to the cytostatic effects of the PI3K/mTOR inhibitor, the drug combination increased tumor cell death in the majority of the PDX models." (PMID 28848242, 2017). "YAP1-silencing led to the concomitant decreased expression of major oncogenic pathways including Kras, mTOR, β-catenin, and M2-promoting IL-4 and tumor-promoting IL-6 cytokines." (PMID 28241877, 2017). "Given its positive role in mTOR pathway and tumor growth, we investigated the expression profile of AKAP1 and its correlation with myc and mTOR in human tumor tissues." (PMID 28569781, 2017). "In a xenograft mouse model of prostate and breast cancer, protein restriction decreased tumor growth and intra-tumor mTOR activity." (PMID 28445443, 2017). "mTOR acts downstream of many tumor suppressor and oncogenic pathways, which tightly regulate its activity under normal circumstances." (PMID 28491867, 2017). "Up-regulating miR-497 in HepG2 and Hep3B cell lines and xenograft models resulted in the down-regulation of IGF1R and mTOR and inhibition of tumor growth and cell invasion." (PMID 28624790, 2017). "miR-199a-3p functions as a tumor suppressor and inhibits tumor metastasis by repressing various oncogenes, such as mTOR,aurora kinase A, and c-MET.Previous analysis have indicated that miR-199a-3p expression is inhibited in various cancer types." (PMID 28743276, 2017). "In conclusion, telmisartan suppressed human EAC cell proliferation and tumor growth by inducing cell cycle arrest via the AMPK/mTOR pathway." (PMID 28052030, 2017). "Although CPT-11 inhibited SW620 tumor growth and downregulated autophagy by mTOR inhibition, apoptotic activity of the drug possibly contributed to tumor reduction." (PMID 29262645, 2017). "We found limited genetic concordance between primary and secondary tumor sites with private mutations in FLT4, MTOR, ITGA5, SETD2, PBRM1, and BRCA1 on progression." (PMID 29088767, 2017). "Overall, our results suggest that miR-497 and miR-99a both function as tumor-suppressive miRNAs by suppressing IGF1R/mTOR signaling pathway." (PMID 28624790, 2017). "It has recently been demonstrated that at the early stages of tumor development MYC not only enhances the overall protein synthesis but also specifically activates mTOR-mediated 4EBP1 phosphorylation, leading to eIF4E oncogene activation." (PMID 28187001, 2017). "Studies employing a combination of Crizitonib together with PF-05212384 or gedatolisib were performed to additionally inhibit the phosphatidyl inositol-3 kinase (PI3K)/Akt/mammalian target of rapamycin (mTOR) signaling pathway in the tumor cells." (PMID 28212658, 2017). "Their results have demonstrated mTOR kinase activation in other models in different tumour cells (HeLa, immortalized astrocytes) after octyl-2-HG treatment or in newly mIDH transfected cells." (PMID 28578659, 2017). "In fact, mTOR inhibition revealed heterogeneous responses, indicating anti-tumor effects in some cases, while others exhibit intrinsic or acquired resistance to the drug both in preclinical or clinical settings." (PMID 29299126, 2017). "Based on our new results, we suggest targeting mTOR activity depending on the metabolic and besides molecular genetic phenotype of tumours to increase the success of therapies." (PMID 28578659, 2017). "In summary, Akt/mTOR signaling pathway inhibition by glipizide sensitizes TRAIL-induced tumor cell death in A549 cells via autophagy flux." (PMID 29245957, 2017).
tumor (continued). "Maertens and colleagues have identified increased activation of the PI3K/AKT/mTOR pathway in BRAF/NF1 double mutants, and a combinatorial MEK marker and mTOR inhibitor treatment has proven effective in many MEK inhibitor-resistant neoplasms." (PMID 28637487, 2017). "To confirm the clinical effectiveness of the dual PI3K/mTOR inhibitor, we isolated and expanded four primary tumor cells from OSCC patients and then treated them with NVP-BEZ235 with and without IR." (PMID 28978144, 2017). "The combination of NVP-BGJ398 with the dual AKT/mTOR inhibitor significantly inhibited tumor growth in comparison with single drug treatments." (PMID 29190880, 2017). "The PI3K- AKT– mTOR- p70S6K1 signaling pathway plays important physiological roles in both normal and tumor cell growth and proliferation." (PMID 28532456, 2017). "The PI3K/AKT/mTOR signaling is a critical pathway in cell proliferation, survival, neovascularization and tumor growth." (PMID 29228721, 2017). "FLCN is considered a tumor suppressor gene and interacts with the mammalian target of rapamycin (mTOR) and adenosine monophosphate-activated protein kinase (AMPK) signaling pathways." (PMID 28069055, 2017). "Essential for tumor growth and survival, mTOR is also a sensor of nutrient level, favoring lipogenesis and inhibiting autophagy." (PMID 29069732, 2017). "Activation of the PI3K/Akt/mTOR pathway leads to chemo-resistance, radio-resistance, tumor cell proliferation, inhibition of apoptosis, and other indirect downstream effects such as increased protein synthesis and induction of angiogenesis via mTOR36." (PMID 29142297, 2017). "Recent studies have indicated the key roles of amino acid transporters along tumor development, especially in regulating the mTOR pathway." (PMID 29088718, 2017). "Clearly, tumor cells possessing these alterations would be inherently resistant to these types of mTOR inhibitors, despite exhibiting high mTOR pathway activity." (PMID 28431544, 2017). "These in vitro findings prompted us to examine the effect of PI3K/AKT/mTOR pathway inhibitors on LMS tumor growth." (PMID 28002802, 2017). "The phosphatidylinositol-3-kinase (PI3K)/Akt/mTOR pathway is also an important molecular signaling pathway in the regulation of tumor cell proliferation." (PMID 29371937, 2017). "Our data argued that for robust ATG13 serine 318 phosphorylation and toxic autophagosome formation to occur, and thus lead to tumor cell death, required both the inactivation of mTOR and the activation of AMPK." (PMID 27903966, 2017). "Intriguingly, LNT remarkably decreased the levels of PI3K, phosphorylated-Akt (p-Akt) and mTOR in MCF-7 tumor tissues." (PMID 29156828, 2017). "Since mTOR activity is high in malignant cancerous tissue, Rapalog counteracts mTOR activity, preventing the formation of tumours." (PMID 28410237, 2017). "The presence of p-mTOR on tumor specimens has been studied for both prognostic and predictive value with opposing results." (PMID 29213282, 2017). "The novel synthetic molecule of the pyridofuropyrimidine class, PI-103, is a potent and selective inhibitor of class I PI3K, mTOR and DNA-PK, which exhibit therapeutic activity against a range of human tumor xenografts." (PMID 28424411, 2017). "We think that under normal physiological condition mTOR is an important player for tumor aggressiveness and inhibition of mTOR pathway results in an effective therapeutic strategy." (PMID 28484222, 2017). "These cell lines were chosen based on Celgene clinical development strategy for CC-115, the potential roles of mTOR and DNA-PK in these tumor types, and commercial availability of the cell lines." (PMID 29088817, 2017). "In several tumor models in which mTOR is massively activated, Deptor levels are much lower than corresponding normal tissue." (PMID 28086984, 2017). "Our study demonstrated that PAK1 is upregulated in PCa and regulated by the mTOR signaling pathway and contributes to tumor autophagy." (PMID 28186966, 2017).
tumor (continued). "The observation that mTOR inhibitors sensitize various tumor xenografts to radiotherapy and chemotherapy further support such a therapeutic approach." (PMID 29104248, 2017). "Numerous inhibitors that target both mTORC1 and mTORC2 complexes, as well as dual PI3K/mTOR inhibitors, are under preclinical and clinical investigation in multiple tumor types." (PMID 27863413, 2017). "The combination of TSC1 and TSC2 functions as a tumor inhibitory complex that suppresses mTOR activity." (PMID 28126011, 2017). "A decrease in the levels of ATP and mitochondrial mass were associated with activation of the metabolic tumor suppressor AMPKα1/2-LKB1, and a reduction in mTOR signaling." (PMID 28473727, 2017). "The interaction between miRNA-497 and IGF1R/mTOR were further collaborated by the inversely correlated expressions of miR-497 and IGF1R/mTOR in HCC tumor tissue and cell lines." (PMID 28624790, 2017). "Despite a clear anti-angiogenic activity of mTOR inhibitors in tumor mouse models, few studies have investigated their effects on tumor endothelial cells in vivo." (PMID 29104248, 2017). "Second, detailed bioinformatic analysis showed that various genes regulating tumor growth, non‐adipogenic differentiation, and the mTOR pathway are regulated by PPARG." (PMID 28275008, 2017). "Another call of therapeutic agents to treat metastasized RCC exhibits anti-tumor effects by inhibition of the mammalian target of rapamycin (mTOR)." (PMID 29165391, 2017). "In contrast, knock down of mTOR enhanced cell death in tumor cells transfected to knock down the expression of AMPK, and to a lesser extent than that caused by ATM knock down." (PMID 27903966, 2017). "The PI3K/AKT/mTOR pathway promotes cell growth and proliferation in many tumor types and is the most important downstream signaling pathway mediated by EGFR in NB cells." (PMID 27902463, 2017). "PTEN is a tumor suppressor gene that antagonizes the PI3K/AKT/mTOR pathway by functioning as a lipid phosphatase." (PMID 29259986, 2017). "SHR8443 showed good pharmacokinetic properties and effectively inhibited mTOR as well as PI3K signaling in tumor tissue after once daily oral dosing." (PMID 29296217, 2017). "The detected decrease of mTOR activity and its correlation with diminished oncometabolite level and tumour growth were also demonstrated in vitro xenografts in our study." (PMID 28578659, 2017). "Some of these effects are obtained by deleting the phosphatase and tensin homolog PTEN, the tumor suppressor gene which acts upstream to mTOR in the mTOR pathway." (PMID 28418837, 2017). "Immunohistochemistry was used to analyze the p-AKT3 and p-mTOR protein levels in isolated tumor tissues." (PMID 29212166, 2017). "In regards to kinase signaling, up-regulation on the protein level in the tumor was detected on both upstream and downstream of the mTOR including AKT1, PI3Kα, GRB2, mTOR, DPTOR, S6K and S6, which is known to be highly mutated in cancer." (PMID 29109428, 2017). "It is worth to note that the levels of unphosphorylated proteins other than HER2, like mTOR, Src and Erk1,2 increased in tumor extracts from resveratrol group." (PMID 28238967, 2017). "We additionally found strong p-mTOR staining in micropapillary UC, which is characterized by small tight clusters of tumor cells within lacunae." (PMID 28831205, 2017). "By targeting both IGF1R and mTOR, miR-497 or miR-99a exerted remarkable tumor suppressive function in vivo and in vitro." (PMID 28624790, 2017). "ThePI3K/Akt/mTOR pathway promotes tumor angiogenesis by altering the activation state of a large number of downstream effector molecules and inducing cell proliferation and inhibiting apoptosis to further promote tumor development." (PMID 29140979, 2017).